CX3CL1 (C-X3-C motif chemokine ligand 1)
Diseases named in the same sentence as CX3CL1 in open-access papers (continued):
Sharing a sentence is not in itself a finding about the gene and the disease.
colorectal cancer (22 papers, 2014 to 2025). A primary or metastatic malignant neoplasm that affects the colon or rectum. "Measuring chemokines and cytokines in plasma of patients with colorectal cancer, high CX3CL1 levels were one of the factors significantly associated with increased overall and cancer-specific mortality." (PMID 40508161, 2025). "Soluble CX3CL1 has been associated with better prognosis in colorectal cancer, has demonstrated antitumor effects in murine lung and hepatocellular cancer models and was identified as a predictor for response to immune checkpoint blockade in patients with non-small-cell-lung cancer." (PMID 38250083, 2023). "In particular, the concentrations of IFN-γ and CX3CL1 were significantly downregulated in the peripheral blood of patients with advanced colorectal cancer, which may be associated with an anti-tumor immune response." (PMID 37063892, 2023). "The expression of CX3CL1 is negatively correlated with the prognosis of colorectal carcinoma patients." (PMID 38049474, 2023). "Accordingly, transient elevated serum levels of CX3CL1 have been described in colorectal cancer patients with anxiety and depression." (PMID 30870525, 2019). "Here we show that the CX3CR1 receptor can be efficiently transduced in human T cells; we have set up an adoptive transfer model in NOD-scid IL-2Rgamma−/− (NSG) mice bearing a human colorectal cancer cell line constitutively expressing the ligand CX3CL1." (PMID 27096098, 2016). "CX3CL1 is considered a prognostic biomarker also for patients with colorectal cancer and hepatocellular carcinoma." (PMID 24799766, 2014). "Thus, we found that CX3CL1-knockdown abrogated MSC inhibition of colorectal cancer, improvement of sensitivity to αPD1 treatment, and modification of CX3CR1high macrophages." (PMID 36843945, 2023). "The results of the analysis of stage IV patients in the previous section strongly suggest the existence of an immune escape mechanism that inhibits NK cell recruitment and anti-tumor function by reducing the level of CX3CL1 in peripheral blood during the progression of colorectal cancer." (PMID 37063892, 2023). "An integrative approach using gene expression, phenome mapping, tissue microarrays and the T-cell repertoire in colorectal cancer also exhibited that a high T-cell presence is correlated to the expression of specific adhesion molecules and chemokines (CX3CL1, CXCL10 and CXCL9)." (PMID 36429101, 2022). "We therefore tested in vivo whether blocking VEGF-A activity would downregulate CX3CL1 in colorectal carcinoma grafts and lead to extravasation of HPMo." (PMID 29367702, 2018). "In addition, the CX3CL1 expression was found to be correlated with good prognosis in colorectal carcinoma." (PMID 28122354, 2017). "Therefore, the combination of MSCs and anti-PD-1 antibody may be a therapeutic approach for colorectal cancer via the CX3CR1/CX3CL1 axis." (PMID 40508161, 2025). "This study discovers that SIRT1, a hub gene involved in glucolipid metabolic conversion in colorectal carcinoma (CRC), stimulates CX3CL1 secretion in CRC cells by activating FOXO1." (PMID 39783838, 2025). "Interestingly, however, while CX3CR1 expression in cancer is generally associated with invasiveness and metastasis, the coexpression of CX3CR1 and CX3CL1 by the same cell type, as occurs in human colorectal cancer cells, acts as a retention factor, limiting tumor spreading to metastatic sites." (PMID 28791023, 2017). "In this respect, CX3CL1 may be considered a chemokine suitable for immunoprevention or gene therapy in colorectal cancer, hepatocellular carcinoma, and, more recently, in gastric adenocarcinoma where its expression correlates with induction of both innate and adaptive immunity." (PMID 24799766, 2014). "In a report using mesenchymal stem cells (MSCs) for the treatment of colorectal cancer, MSCs induced CX3CR1-high expressing macrophages and promoted M1 polarization, which inhibited tumor growth by promoting CX3CL1 secretion." (PMID 40508161, 2025).
colorectal cancer (continued). "Chemokines, including CXCL10, CXCL12, CX3CL1, CCL2, CCL5, CCL18, and CCL20, induce chemotaxis to promote cell migration and invasion in ovarian, lung, breast, and colorectal cancers." (PMID 38438872, 2024). "For these reasons, increasing the expression of CX3CL1 and CX3CR1 in the tumor simultaneously improves the prognosis of patients with cancers such as colorectal cancer and hepatocellular carcinoma." (PMID 32466280, 2020). "Two human colorectal cancer cell lines were used to set up a xenograft tumor model in immunodeficient mice; the NCI-H630, constitutively expressing the chemokine ligand CX3CL1 (Fractalkine), and the RKO cell line, transduced to express CX3CL1." (PMID 27096098, 2016). "Differential gene profiling analysis of tumor vs. non-tumor samples from surgical colorectal cancer patients showed that CX3CL1 and CX3CR1 were significantly upregulated in tumors." (PMID 40508161, 2025).
prostate carcinoma (22 papers, 2006 to 2025). A carcinoma that arises from epithelial cells of the prostate gland. "Hypoxia causes upregulation of CX3CL1 secretion and expression and enhances cell proliferation by promoting cell cycle progression in prostate cancer cells." (PMID 40508161, 2025). "In breast and prostate cancer a higher expression of CX3CL1 is associated with the occurrence of metastasis." (PMID 29867042, 2018). "CX3CL1/CX3CR1 is an important factor in bone metastasis of prostate cancer because prostate cancer cells express CX3CR1 and bone marrow endothelial cells and osteoblasts express CX3CL1." (PMID 40508161, 2025). "In prostate cancer studies, osteoblasts have been found to express soluble and membrane‐bound CX3CL1, which promotes prostate cancer to metastasize and colonize bone tissue." (PMID 33191645, 2021). "During the early phase of metastasis, cytokines such as TGFβ, IL-6, CXCL8, IL-7, CXCL16, and CX3CL1 induce EMT in prostate cancer cells and transforms them to exhibit higher migratory and invasive potentials." (PMID 32585812, 2020). "In this study, we have shown that CD9+ halos surround lymphatic vessels in human prostate cancer specimens and that EEV fractions promoted the migration of CX3CR1+ human PC3-ML prostate cancer cells in a CX3CL1-dependent manner." (PMID 29650776, 2018). "In prostate cancer, Shulby and colleagues demonstrated in vitro that CX3CL1 and its receptor direct prostate cancer cells to the bone marrow and guide their preferential migration towards human osteoblasts." (PMID 24799766, 2014). "Bone marrow endothelial cells express the membrane form of CX3CL1, that is cleaved by osteoblasts and released as soluble molecule able to attract prostate cancer cells." (PMID 24799766, 2014). "However, the recurrence rate of prostate cancer in patients after prostatectomy was lower with higher expression of CX3CL1 in prostate tissue." (PMID 40508161, 2025). "Previous studies have suggested oncogenic functions of CX3CR1 in prostate cancer, as the expression of CX3CR1 in prostate cancer epithelial cells directs their circulation to the bone, and CX3CL1/CX3CR1 enhance the migration and metastasis of prostate cancer cells." (PMID 38781024, 2024). "In addition, in prostate cancer cells, CX3CL1 is involved in EGFR transactivation and expression of Slug." (PMID 31077234, 2019). "For example, chemokine ligand 17 (CCL17), promotes the stemness, EMT process, the TGF-β1 and Wnt/β-catenin signaling in MHCC97L cells; chemokine (C-X3-C motif) ligand 1 (CX3CL1), participates in the molecular events that regulate cell adhesion, migration and survival of human prostate cancer cells." (PMID 27258544, 2016). "Previous research has demonstrated that CX3CL1 plays a crucial function in numerous types of cancers, including ovarian carcinoma, B-cells lymphoma, neuroblastoma, breast cancer, gastric cancer, pancreatic cancer, prostate cancer, colorectal cancer, lung cancer, and hepatocellular cancer." (PMID 37153002, 2023). "Abnormal levels of inflammation-related serum proteins, such as C-X3-C motif chemokine ligand 1, platelet-derived growth factor subunit B homodimer, interleukin 10, C-C motif chemokine ligand (CCL) 21, and CCL 11, were also found to be related to the risk of prostate cancer." (PMID 32722165, 2020). "CX3CL1/CX3CR1 induced EMT and migration and invasion of androgen-independent prostate cancer cells via TACE/TGF-α in several prostate cancer cell lines under hypoxic conditions." (PMID 40508161, 2025). "CX3CL1 has been reported to promote metastasis of different tumor types, and CX3CR1 has been found to be overexpressed in prostate cancer tissues with spinal metastasis." (PMID 32585812, 2020). "Further in vitro experiments showed that CX3CL1 promoted BG1 cell proliferation through its binding to CX3CR1 as well as AKT activation, as previously reported for human prostate cancer cells." (PMID 21750716, 2011).
prostate carcinoma (continued). "Both CX3CL1 and CCL4 are chemokines involved in attracting immune effector cells, such as natural killer cells and T lymphocytes, although they appear to exert opposing influences on prostate cancer behavior." (PMID 41065832, 2025). "CX3CL1’s unique receptor CX3CR1 is expressed by a wide variety of immune cells and tumor cells in malignancies such as multiple myeloma, metastatic pancreatic cancer, prostate cancer and lymphocytic leukemia." (PMID 37153002, 2023). "Thus, CX3CL1/CX3CR1 is involved in prostate cancer metastasis and may be a target for prostate cancer therapy." (PMID 40508161, 2025).
hepatocellular carcinoma (21 papers, 2014 to 2025). A malignant tumor that arises from hepatocytes. "It has been reported that CX3CL1 expression is closely associated with cancer cell metastasis in prostate, gastric, and breast cancer, as well as in renal and colon carcinoma and hepatocellular carcinoma (HCC) in spinal metastases." (PMID 39329945, 2024). "Inhibition of the binding of CacyBP-MyD88 could reduce fractalkine (CX3CL1) secretion and thus weaken the recruitment of tumor-associated macrophages (TAMs) to the immune microenvironment, making hepatocellular carcinoma mice sensitive to programmed death 1 (PD-1) treatment." (PMID 38785969, 2024). "Spinal metastases in hepatocellular carcinoma patients also have high CX3CL1 and CX3CR1 expression, and CX3CL1 promoted hepatocellular carcinoma cell migration in vitro and spinal metastasis in vivo." (PMID 37025604, 2023). "Previous studies have found that miR-590-3p targeted CX3CL1 to regulate the progression of hepatocellular carcinoma." (PMID 34898373, 2022). "In vitro studies have shown that CX3CL1 is a direct downstream target of miR-561-5p, a microRNA that has been associated with pulmonary metastasis and a poor prognosis in hepatocellular carcinoma (HCC) patients." (PMID 33391453, 2021). "In this context, the attraction of splenic lymphocytes by supernatants of CX3CL1 transduced murine hepatocellular carcinoma or neuroblastoma cells was shown." (PMID 29867042, 2018). "Moreover, in hepatocellular carcinoma patients, a good prognosis and low recurrence rates are related to high expression levels of CX3CL1/CX3R1." (PMID 35596772, 2022). "Higher expression of CX3CL1/CX3CR1 correlates with better prognosis and fewer recurrences in hepatocellular carcinoma." (PMID 34316701, 2021). "CX3CL1 expression levels differ among HBV genotypes, and its expression in HBV-replicating hepatocytes and hepatoma cells may contribute to the immunopathogenesis of HBV infection." (PMID 40733585, 2025). "With specific concern on HBV chronic infection, it was demonstrated that a differential expression of CX3CL1 produced by HBV-infected hepatocytes and hepatoma cells can affect the migration activity of CX3CR1+ immune cells, potentially contributing to the immunopathogenesis of HBV infection." (PMID 40733585, 2025). "In addition to its favorable involvement in gastric adenocarcinoma regarding disease-free survival, CX3CL1 has also been documented to boost the immune system’s anti-tumor activity against LIHC and improve the prognosis of patients with hepatocellular carcinoma." (PMID 37153002, 2023).
COVID-19 (17 papers, 2020 to 2025). A disease caused by infection with severe acute respiratory syndrome coronavirus 2. "In COVID-19 patients, increased CX3CL1 is associated with disease severity, and patients with neurological syndrome (NS) presented with higher CX3CL1 levels than non-NS patients." (PMID 35464491, 2022). "Similarly, high levels of CX3CL1 (above 433 ng/mL) were also associated with a longer duration of illness in COPD patients with COVID-19." (PMID 40861638, 2025). "This proposed mechanism, supported by prior literature, suggests that CX3CL1-mediated immune cell recruitment may amplify pulmonary damage through excessive inflammation, while elevated D-dimer reflects COVID-19-associated coagulopathy driving thrombosis." (PMID 40861638, 2025). "Moreover, the levels of CX3CL1 were associated with the duration of illness in severe COVID-19." (PMID 38674036, 2024). "The degree of negative correlation of IL12p40 and CX3CL1 with inflammatory factors gradually increased depending on COVID-19 severity, suggesting that suppression of IL12p40 and CX3CL1 might be associated with enhanced inflammatory responses driving critical pneumonic progression in patients." (PMID 36776879, 2023). "Thus, CX3CL1 may serve as a predictive marker for identifying COVID-19 patients who are at risk of developing thrombotic complications and require more aggressive anti-thrombotic management." (PMID 35464491, 2022). "During COVID-19 infection, the levels of CX3CL1 in the serum inflammatory mediators were higher in critically ill patients than those in severe COVID-19 patients." (PMID 38674036, 2024). "Increased CX3CL1 can promote a pro-thrombotic environment and enhance immune cell recruitment, leading to more severe COVID-19 and mortality." (PMID 35464491, 2022). "The relationship between CX3CL1 and endothelial damage in COVID-19 patients suggests that elevated CX3CL1 levels could exacerbate thrombotic events." (PMID 40861638, 2025). "Monitoring CX3CL1 levels could help identify COVID-19 patients who require more aggressive antithrombotic treatment, thereby improving clinical outcomes." (PMID 40861638, 2025). "The CX3CL1 predicts better in-hospital mortality in COPD patients with COVID-19." (PMID 40861638, 2025). "In a study, it was found that CX3CL1, D-dimer, procalcitonin, and Interleukin-6 could effectively predict mortality in patients with severe COVID-19." (PMID 38611597, 2024). "Other data have shown that the occurrence of new or more severe headaches due to COVID-19 elicited peripheral sensitization and microglial activation associated with serum changes in BDNF, TGF-ß1, VEGF, NGF, and CX3CL1 suggestive of long-lasting severe inflammation or immune dysregulation." (PMID 39596862, 2024). "Moreover, the levels of IL-8, CCL2, CCL3, CCL4, CCL7, CCL12, and CX3CL1 were higher in both the serum and CSF samples of COVID-19 cases with neurological syndrome (NS)." (PMID 35464491, 2022). "Increased levels of cerebrospinal fluid chemokines, including CX3CL1, might facilitate the trafficking of monocytes to the cerebrospinal fluid, and potentially contribute to the development of neurological symptoms in patients with COVID-19." (PMID 38674036, 2024). "In our study, TGF-β1, VEGF, CX3CL1 and β-NGF were elevated in patients with more severe headaches after COVID-19." (PMID 38890625, 2024). "Only convalescent COVID-19 patients with cardiovascular risk had a higher SELP+ CEC count (p=0.0291), while a higher CX3CL1+ CEC count was found only in non-COVID-19 cardiovascular risk patients (p=0.0462)." (PMID 33752798, 2021). "More mature CD62L−NKG2A− CD56dim NK cells express higher levels of CX3CR1 compared with less mature NKG2A+ and CD62L+ CD56dim NK cells, and the CX3CR1 ligand CX3CL1 was one of the few chemokines that were not induced in BAL from COVID-19 patients." (PMID 32826343, 2020).
COVID-19 (continued). "Conversely, and regardless of vaccination status, antibodies to CCL19, CCL8, CCL13, CCL16, CXCL7 and CX3CL1 significantly increased, those to CXCL17 remained generally stable and those to CCL22 followed variable kinetics at month 12 compared with month 6 in the COVID-19 convalescents." (PMID 36879067, 2023). "Furthermore, a clear clustering of cytokines (IL-6, TNF-α, IFN-γ, IFN-α, SDF-1α, MIP-1α, MIP-1β, G-CSF, IL-10, CX3CL1 and IL-4) was observed in a PCA for critically ill COVID-19 patients during the first wave who presented a bacterial superinfection during their stay at the ICU." (PMID 35007290, 2022). "An elevated IFNA1 response displayed a strong negative correlation with IL12p40 and CX3CL1, whereas it presented a robust positive correlation with CCL11, FASLG, and IL23A, especially in severe COVID-19 patients." (PMID 36776879, 2023). "This corroborates with our data where, contrary to CCL2, serum CX3CL1 was quicky augmented suggesting that non-classical monocytes (NC; CD14+/-CD16++/CX3CR1+) rather than classic monocytes (CL; CD14++CD16−/CCR2+) are the first actors during COVID-19." (PMID 40710346, 2025).